GZMB (granzyme B)
Diseases named in the same sentence as GZMB in open-access papers (continued):
Sharing a sentence is not in itself a finding about the gene and the disease.
tumor (continued). "For example, SG enhances tumor sensitivity to anti-PD-1 therapy by recruiting natural killer (NK) or CD8+ T cells to infiltrate the TME, where they secrete interferon-gamma and granzyme B to mediate tumor cell cytotoxicity." (PMID 39555080, 2024). "As we previously discovered that CAR T cell killing of NALM6 tumor cells remains unaffected by GZMB inhibition and FasL blocking, we next investigated the contribution of GZMA in CAR T-mediated killing." (PMID 38307835, 2024). "NK cells, an essential component of the innate immune system, exhibit the ability to directly eliminate tumor cells through the secretion of cytotoxic molecules such as GZMB and PRF1." (PMID 39439794, 2024). "In this study, we investigated the killing capability of NK cells and CTLs to produce perforin and granzyme-B in different regions, including the core tumor infiltration region of the TME and the marginal infiltration zone of paracancerous tissues." (PMID 38341587, 2024). "We show a significantly lower frequency of reporter activity in NALM6-PI9-GBR killing events compared to NALM6-GBR confirming that PI9 overexpression directly inhibits GZMB activity in the tumor cell cytosol." (PMID 38307835, 2024). "CD8 T cells, after recognition of tumor-specific antigens, work through multiple mechanisms to confer anti-tumor activity, including the release of cytokines, granzyme B, and perforin or by engaging death receptor ligands." (PMID 39104861, 2024). "Granzyme B represents the final signal under multiple immune regulatory pathways, reflecting the targeted killing ability of CTLs on tumor cells." (PMID 38869633, 2024). "A direct link between ILC2s and CD8+ CTLs was demonstrated by observing elevated levels of granzyme B and increased killing of tumor cells by CTLs during co-culture in the presence of ILC2s but not in their absence." (PMID 38524132, 2024). "We also observed a significantly higher frequency of strongly activated CD43+ CD8+ T-cells expressing the cytotoxic molecule granzyme B (GzmB) in tumours of IAV-infected mice." (PMID 38271469, 2024). "Firstly, the infiltration of T cells (CD3, CD4, CD8, GZMB), tumor-associated macrophages (TAMs, CD11b), B cells (CD24) and NK cells (CD56) within the tumor was assessed by immunohistochemical (IHC) staining." (PMID 38622609, 2024). "For example, chemotherapy-induced upregulation of mannose-6-phosphate receptors on the tumour cell surface enhances the penetration of T cells into the tumour site and increases the permeability of tumour cells to granzyme B in a perforin-independent manner." (PMID 39450176, 2024). "This Ly6a+ GzmB+ population also expressed significantly more Tcf-1 compared to tumor infiltrating TEX, and significantly less than the canonical TSTEM in the TdLN consistent with the transcriptional results." (PMID 38496632, 2024). "In this regard, we found significantly increased proportions of highly activated CD43+ gp100-specific CD8+ T-cells that also expressed GzmB when the tumour-bearing animals were infected with IAV." (PMID 38271469, 2024). "More importantly, we showed that hypoxia-induced autophagic degradation of granzyme B in tumor target cells is a new mechanism of hypoxic tumor cell escape from NK cell-mediated lysis." (PMID 39598355, 2024). "Chemotherapy can inhibit suppressive immune cells, leading to the increased persistence of CAR-T cells, and sensitize tumor cells to CAR-T cell activity by enabling granzyme B penetration into tumor cells." (PMID 39456909, 2024). "Another granzyme B-targeted tracer, 68Ga-grazytracer, showed comparably higher uptake at tumor sites than 68Ga-NOTA-GZP." (PMID 39072335, 2024). "As expected, the reduction in PD-L1 expression in KEAP1-overexpressing cells led to an upregulation of tumor immunity, evidenced by elevated levels of total and activated CD8+ cytotoxic T cells (GzmB+) within tumor-infiltrating lymphocytes." (PMID 38413563, 2024).
tumor (continued). "Meanwhile, when co-cultured with GBP5-overexpressed HEY cells, the transcriptions of CCR5/7, which are crucial markers mediating T cell tumor infiltration 46, 47, were notably upregulated in T cell, simultaneously with a decrease in GZMB transcription." (PMID 38817865, 2024). "Measuring granzyme-B activity allows for a readout of activated T cells instead of just T cell presence within the tumor immune microenvironment." (PMID 39104861, 2024). "Anti-tumour efficacy and cytotoxic T lymphocyte signature were examined through tracking granzyme B, IFN-γ, IL-2 secretion levels, and flow cytometry analysis of proliferation." (PMID 38581063, 2024). "Not only do MMRd tumors contain higher numbers of tumor-infiltrating T cells, but these T cells also have higher expression of activation and cytotoxic markers such as IL-2Rα, granzyme B, perforin, PD-1 and IFN-γ." (PMID 39544936, 2024). "This resulted in a decrease in regulatory T cells and a decrease in tumor-infiltrating myeloid-derived suppressor cells, along with an increase in granzyme B and interferon-gamma (IFN-γ), and effector T-cell activation." (PMID 38256070, 2024). "What’s more, we have conducted an evaluation of the number of regulatory T cells (Tregs) or the percentage of Granzyme B+ and IFN-γ+CD8+T cells in HA15-treated tumor harboring IRE1α or XBP1 deficiency using immunofluorescence staining analysis." (PMID 38291473, 2024). "The granzyme B response and tumor cell apoptosis under FCCP/oligomycin A conditions was comparable to that with T cell stimulation alone." (PMID 38515569, 2024). "The striking presence of functional granzyme B+ perforin+ cNK cells in this tumor suggests an active TIME comprised of largely responsive NK cells." (PMID 39076998, 2024). "This resulted in reduced numbers of tumor-infiltrating T cells, granzyme B+ cells and DCs, overall leading to immune evasion and enhanced tumor growth." (PMID 39544936, 2024). "The finding of tumor cell apoptosis corresponds with the increased expression of granzyme B by T cells following sotigalimab and the induction of granzyme-expressing CD8+ T cell clones post-sotigalimab." (PMID 38181044, 2024). "The frequency of tumor-infiltrating CD11c+ DCs and GzmB+ T cells was markedly increased in the resected tumors." (PMID 38821980, 2024). "A glycoprotein isolated from Zanthoxylum piperitum DC (ZPDC) fruit induces tumor cells to secrete perforin and granzyme B, activating NKs and enhancing tumor immunosurveillance in liver cancer tissues in vivo." (PMID 38792234, 2024). "Cytotoxic CD8 + T cells possess the capability to directly eliminate tumor cells by releasing perforin and granzyme B, mediating apoptosis through the Fas/FasL pathway, or secreting cytokines." (PMID 39078518, 2024). "Since CD8+ and GzmB+ cells infiltrated from parenchyma surrounding the metastases, we evaluated the cell density within the tumor and the peritumoral area within 500 μm." (PMID 39231916, 2024). "Expressions of Cd8, Tbx21 and Granzyme B in tumor tissues of ACY-1215 monotherapy group and anti-PD1 monotherapy group were higher than those of control group." (PMID 38231305, 2024). "Recently, granzyme‐B responsive linkers have been developed for PET imaging of granzyme B activity and further used for monitoring tumor response to immunotherapy." (PMID 39175888, 2024). "Collectively, elevated GBP5 expression in T cells potentially promotes T cell activation and infiltration, while simultaneously reducing the release of tumor-killing molecules, as evidenced by the downregulation of GZMB and IFNγ transcription in Jurkat cells." (PMID 38817865, 2024). "This was associated with increased expression of IFNγ and granzyme B by CD4+ and CD8+ T cells of tumor-bearing Ac-CD4Cre mice compared to wt littermates." (PMID 38919612, 2024). "ML NK cells devastate tumor cells by producing granzyme B and perforin and expressing CD16 and CD57." (PMID 39205940, 2024).
tumor (continued). "The data indicate that Tr1 cells eradicate TAMs using a granzyme B and perforin-dependent mechanism, which enhances tumor growth." (PMID 38509593, 2024). "In CAR-T Cell Therapy, CAR-T cells induce pyroptosis in tumor cells by activating the caspase-3/GSDME pathway through GzmB release." (PMID 38987821, 2024). "Particularly for CD8 T cells, the expression of granzyme B, a major effector molecule for direct tumor killing, was also decreased with macrophage depletion." (PMID 38517331, 2024). "The HER2-CD3-Fc bsAb in the culture significantly enhanced T cell secretion of IFN-λ, TNF-α, and granzyme B in response to NCI-H460 tumor cells in a dose-dependent manner." (PMID 39066446, 2024). "CD8 T cells, assisted by CD4+ T cells, can trigger the STAT3-Granzyme B (GzmB) pathway to eliminate tumor cells." (PMID 38672681, 2024). "As the data with our genetic reporter based assays confirm, overexpression of PI9 does directly reduce GZMB activity in tumor cells." (PMID 38307835, 2024). "The results of this study showed that high-dose AA increased the intratumoral infiltration of CD4+ and CD8+ T cells and macrophages into the tumor microenvironment, with increased production of granzyme B and interleukin-12." (PMID 39896806, 2024). "The recruitment of tumor-infiltrating CD11c+ DCs and cytotoxic GzmB+ immune cells was also elevated in the triple-treatment group." (PMID 38564022, 2024). "γδ T cells can degranulate and release perforin, GzmB and granulysin as effector molecules to induce apoptosis in tumor cells." (PMID 39061247, 2024). "Further characterization of the tumor cells revealed granzyme B activity in HROC113 as well as HROC285 T0 M2, which was found independent of IFNγ treatment." (PMID 39075115, 2024). "High TIL and its subset (CD4+, CD8+, CD56+, CD57+, GNLY+, and GZMB+ TIL) infiltration correlated with favorable clinicopathological features of tumor." (PMID 39643914, 2024). "GFI treatment also reduced the mRNA and protein expression of TIGIT, and increased the expression of granzyme B to restore and activate T cell response in the tumor micro-environment." (PMID 38169590, 2024). "More importantly, the proportions of tumor‐infiltrating IFNγ+, GZMB+, and TNFα+ CD8+ T cells were significantly elevated after SRC‐1 deletion, indicating more effector CD8+ T cells were activated." (PMID 38953362, 2024). "The level of granzyme B + CD4 + T cells was increased in both single PAK KO tumours, with a further significant increase in PAK1&4 double KO." (PMID 38797819, 2024). "It functions as a cytotoxic cytokine, working alongside granzyme B and perforin to induce apoptosis in tumor cells." (PMID 39769153, 2024). "Deeper characterization of the phenotype of NK cell subsets within the tumor showed a lower expression of the cytotoxicity-mediating molecules granzyme B and perforin as well as CD16 within the CD49a+ subset." (PMID 38267402, 2024). "Activated CD8+ T cells migrate to the tumor region to release cytotoxic molecules such as IFNγ, TNFα, perforin, and granzyme B, which activate anti-tumor immune responses and induce apoptosis in tumor cells." (PMID 39776907, 2024). "A significant increase in non–tumor cell granzyme B content was observed, suggesting an increase in T cell and NK cell cytotoxicity against tumor cells." (PMID 38912584, 2024). "Histopathological examination of the tumor showed an increased number of tumor-infiltrating lymphocytes and enhanced expression of granzyme B by this drug combination." (PMID 38167322, 2024). "Another mechanism of anti-tumor activity involves B cells producing granzyme B (GZMB) to directly target and destroy tumor cells." (PMID 39519376, 2024). "NK cells can not only provoke tumor cell apoptosis through their direct natural cytotoxicity (e.g., granzyme B and perforin); they can also control tumor growth via secreting cytokines or regulating the activity of other inflammatory cells." (PMID 39061427, 2024).
tumor (continued). "The expression of tumor cell-killing factors such as interferon-γ, tumor necrosis factor-α, and granzyme B by T cells was significantly increased, resulting in enhanced tumor cell killing." (PMID 38560505, 2024). "Proportion of granzyme B (GZMB)-expressing CD8 T cells in tumor nest of TME was significantly increased in the combination group compared to the control group (18.81 ± 10.36 and 4.09 ± 1.55, respectively, P < 0.05)." (PMID 38916448, 2024). "Effector CD8+ T cells, commonly referred to as CTLs, primarily exert their anti-tumor effects through the release of perforin and granzyme B(GZMB), which mediate tumor cell lysis and apoptosis." (PMID 39456702, 2024). "Concurrently, intracellular cytotoxic molecules or cytokines were stained to assess the functionality of CAR-T cells in the tumor by measuring their production of Granzyme B and IFN-γ." (PMID 38468291, 2024). "In mice, ectopic GSDME expression in Gsdme-repressed tumors inhibited tumor growth mediated by Granzyme B in killer cytotoxic lymphocytes, which cleaved and activated GSDME in target cancer cells, leading to caspase-independent pyroptosis." (PMID 38195694, 2024). "Once in the tumor, 3034 can be specifically liberated from the backbone to inhibit Sb9, thereby reactivating the activity of GzmB to enhance cancer immunotherapy." (PMID 38966643, 2024). "Further examination of intracellular levels of IFN-γ, granzyme B, PD-1, and Tim-3 in tumor-infiltrating lymphocytes illuminated changes in the immune functionality of CD8+ T cells." (PMID 38577598, 2024). "In the granule exocytosis pathway, perforin 1 delivered Granzyme B (GZMB) into tumor cells and induced tumor cell death." (PMID 38360696, 2024). "Additional examinations revealed granzyme B activity in both tumor cell lines HROC113 and HROC285 T0 M2, accompanied by the expression of its inhibitor PI-9." (PMID 39075115, 2024). "Nevertheless, we detected that the mRNA and protein expression of granzyme B were elevated in GFI-treated 4T1 tumor-bearing mice." (PMID 38169590, 2024). "Overexpression of SUMO2 in T cells suppresses tumor growth in vivo, linking to higher mRNA levels of IFN-γ and granzyme B in tumor tissues." (PMID 38280996, 2024). "Especially, high numbers of infiltrating TIGIT+CD8+ T cells into the tumour diminish the anti-tumour immunity, associated with a low expression of TNF-α, IFN-γ, and GzmB." (PMID 38893071, 2024). "In tumour tissues, the abundance of GzmB, perforin, TNF-α, and IFN-γ is significantly decreased in CD4+, CD8+ T cells, and NK cells compared to non-tumour tissues." (PMID 38893071, 2024). "The transferred CTLs pretreated with UA substantially enhanced the IFN‐γ, TNF‐α, IL‐2, and granzyme B‐producing capacity in the tumor, spleen, and lymph node." (PMID 38447147, 2024). "The population of T cells was also regulated upon rivaroxaban treatment, reducing the immune-suppressive regulatory CD4+ FoxP3+ T cells and increasing tumor-killing granzyme B+ CD8 T cells." (PMID 37444590, 2023). "Granzyme B is a serine protease released by cytotoxic T cells at the end of anti-tumor immune pathways, leading to tumor cell death." (PMID 38067379, 2023). "Using flow cytometry, PV-1 was found to induce significant decreases in the frequencies of both splenic and tumor g-MDSCs, resulting in increased expression of granzyme B, TNF-α and IFN-γ by CD8+ cells." (PMID 38077406, 2023). "The immune response of γδ T cells is biased towards type I immunity and kills tumor cells mainly by producing granzyme B and perforin." (PMID 38057852, 2023). "In 4 of 17 ccRCC specimens, there was a significantly higher expression of granzyme B-positive cells in the tumor periphery when compared to the tumor center (p ≤ 0.05)." (PMID 37894418, 2023). "In TC, we are the first to show that tumor-associated mast cells exhibit a strong inhibitory role on CD8+ T-cell proliferation and granzyme-B secretion in a galectin-9-dependent manner." (PMID 37042867, 2023).
tumor (continued). "Surprisingly, radiation therapy increased the level of PD-L1 expression but also increased the number of Granzyme B+ T lymphocytes in tumor tissues, indicating that factors other than PD-L1 also inhibit T lymphocyte function." (PMID 37640735, 2023). "There was some evidence demonstrating that CAR-T cells exert their tumor-killing effects by producing granzyme B and perforin after recognition." (PMID 37308954, 2023). "The levels of granzyme B expression usually reflect the potency of CTL cytotoxicity against tumor cells." (PMID 37986544, 2023). "Of significance, the expression of coinhibitory receptors (PD1, KLRG1, LAG3, and TIM3) was considerably lower in CD8+ T cells retrieved from B16 Mgst1 KD tumor, and there was an increase in cytokine response (IFNγ and TNFα) along with Granzyme B." (PMID 37321450, 2023). "Hypoxia in TME favors metastatic tumor cells for avoiding NK cell elimination by releasing TGFB1 and miRNAs through exosome to target NKG2D and trigger cell autophagy to block tumor cells to GZMB-mediated lysis." (PMID 37190251, 2023). "CD8+ T-lymphocytes are cytotoxic cells that destroy tumor cells by inducing cytolysis with the granzyme B-perforin complex." (PMID 36627701, 2023). "Analysis of tumor tissue samples from the combination treatment group revealed a significant increase in the presence of GZMB+ and CD8+ T cells." (PMID 37326784, 2023). "CD8 + T cells can secrete IFN-γ to destroy tumors, and another crucial mechanism involves perforating tumor cells and mediating tumor cell death through granzyme B, which primarily functions through caspase-3." (PMID 37438720, 2023). "As a consequence, the production of tumor-infiltrating granzyme B and IFN-γ by CD8+ T cells in ATXN3-KO tumors was significantly increased." (PMID 38038129, 2023). "B lymphocytes can enhance the cytotoxic activity of T cells, the phagocytosis by macrophages, the NK cells’ function of tumor killing, the tumoricidal effect by granzyme B secretion, and the CD4+ and CD8+ T cells’ priming." (PMID 37046842, 2023). "As T cell cytotoxicity indicators, interferon gamma (IFNγ), and cytolytic granule enzyme Granzyme B (GZMB) had greater expression levels in the CD8 T cells of the tumor organoids when they were treated with ITF2357, I‐BET151, or JQ1." (PMID 37271874, 2023). "This interpretation is consistent with higher gene expression of effector- and division-associated genes (GZMB, IFNG, MKI67) in the untreated tumor and low expression of activation markers such as HLA-DR and CD38 in the irradiated tumor." (PMID 37209684, 2023). "On-treatment, responsive tumours contained abundant granzyme B+ T cells, whereas resistant tumours were characterized by CD15+ cancer cells." (PMID 37674077, 2023). "In inflamed tumours, defined as having high lymphocytic infiltration, dual granzyme B and CD8 staining was more frequent in responding (87%) versus relapsing tumours (30%)." (PMID 37511609, 2023). "In animal models, lenvatinib, a multiple receptor tyrosine kinase inhibitor, was demonstrated to reduce tumour-associated macrophages and increase the percentage of activated CD8+ T cells secreting interferon (IFN)-γ + and granzyme B (GzmB)." (PMID 36854710, 2023). "Murine responders had increased tumor-infiltrating T cells, augmented granzyme B expression, and fewer regulatory T cells." (PMID 37446056, 2023). "T-cells obtained from mice that were vaccinated displayed tumor-specific cytotoxicity, as shown by enhanced tumor cell killing in co-culture experiments, accompanied by increased levels of Granzyme B, TNF-α, IFN-γ, and CD107a in T-cells." (PMID 37434263, 2023). "Some authors reported that NK cells release perforin that binds to tumor cell membrane, creating transient pores and Ca2+ cell influx to vehicle granzyme B granules into target cells by clathrin- and dynamin-dependent endocytosis." (PMID 38071322, 2023).